RN7SL750P (RNA, 7SL, cytoplasmic 750, pseudogene)
Gene: Miscellaneous RNA gene on chromosome 7 (100,821,027 to 100,821,264, reverse strand). Ensembl gene ENSG00000263672.
Homologues: Orthologues: chimpanzee Metazoa_SRP (96% identical), macaque Metazoa_SRP (86% identical). Paralogues in human: RN7SL488P (82% identical), RN7SL391P (82% identical), RN7SL474P (81% identical), RN7SL96P (81% identical), Metazoa_SRP (81% identical), RN7SL622P (81% identical), Metazoa_SRP (80% identical), RN7SL134P (80% identical), RN7SL510P (80% identical), RN7SL811P (80% identical), RN7SL163P (80% identical), RN7SL339P (80% identical), and 708 more.